SIRT6 (sirtuin 6)
Diseases named in the same sentence as SIRT6 in open-access papers (continued):
Sharing a sentence is not in itself a finding about the gene and the disease.
neurodegenerative disease (17 papers, 2016 to 2025). A disorder of the central nervous system characterized by gradual and progressive loss of neural tissue and neurologic function. "Lastly, we reveal that the changes driven by SIRT6 loss also occur in neurodegenerative diseases and aging brains, suggesting that age-dependent SIRT6 decay plays a causal role in neurodegenerative diseases." (PMID 36653345, 2023). "Importantly, signs of mitochondrial dysfunction observed in SIRT6-deficient brains were also found in the aged brain and especially in the brain with neurodegenerative diseases, such as Alzheimer’s, Parkinson’s, Huntington’s, and ALS." (PMID 38016059, 2023). "Increased signs of DNA damage, cell death, and hyperphosphorylated Tau, all features of neurodegenerative diseases, were observed in SIRT6-deficient mice brain indicating the importance of SIRT6 regulation of DNA repair and maintenance of genomic stability to keep the brain healthy." (PMID 33414704, 2020). "Sirtuin 6 has been reported to be important in the protection against age-related and neurodegenerative diseases in the brain." (PMID 36653345, 2023). "It not only reveals a pivotal role in brain development, but also shows a close relationship between the aberration of SIRT6 with human neurodegenerative diseases." (PMID 33855020, 2021). "In this study, it was observed that the brain was underdeveloped, suggesting low levels of Sirt6 can lead to neurodegenerative diseases and brain aging." (PMID 33442387, 2020). "The ubiquity of neurodegenerative diseases is increasing, and decreased levels of Sirt6 in degenerative disease animal models have given a clear understanding of its role, especially in AD." (PMID 33442387, 2020). "Similarly, many studies have reported that SIRT6 suppresses TNF-α in a neurodegenerative disease model." (PMID 40508105, 2025). "The functional relevance of SIRT6 depletion in the aging brain and neurodegenerative diseases could influence the capacity of REST to protect the brain from neurodegeneration." (PMID 39511137, 2024). "Preventing the reduction of SIRT6 expression or augmenting SIRT6 activity might thus provide a therapeutic opportunity to reinstate mitochondrial homeostasis in the brain and prevent neurodegenerative diseases." (PMID 36653345, 2023). "For example, brain-specific Sirt6 knock-out mice show signs of early brain aging, like behavioral and major learning impairment and the stabilization of Tau protein, which are characteristics of different neurodegenerative diseases." (PMID 34720996, 2021). "SIRT6 has been reported to impact brain aging and neurodegenerative diseases such as AD." (PMID 33920726, 2021). "All of this put together shows that there may be a strong link between SIRT6 and neurodegenerative diseases." (PMID 29966233, 2018). "A study showed that SIRT6 plays a pathogenic and pro-inflammatory role in PD, and that nicotine can provide neuroprotection by accelerating its degradation, suggesting that the inhibition of SIRT6 may be a promising strategy for ameliorating PD and other neurodegenerative diseases." (PMID 39683859, 2024). "In addition, studies have found that SIRT6 also promotes the production and secretion of inflammatory cytokines, leading to chronic inflammation, which is the basis of neuronal death in Parkinson’s disease and other neurodegenerative diseases." (PMID 33855020, 2021). "Also, Sirt6 DSB repair functions become relevant in neurodegenerative diseases." (PMID 34720996, 2021). "Due to the young age of the examined animals in both of these SIRT6 KO models, it is not clear if SIRT6-related pathologies are developmental or indeed representative of age-related degenerative diseases." (PMID 28448551, 2017).
kidney diseases (13 papers, 2017 to 2025). "Relevant studies manifest that aberrant nicotinamide adenine dinucleotide-dependent protein deacetylase sirtuin-6 (SIRT6) is available to aggravate renal insufficiency, renal tubular injury, and renal fibrosis, which is closely associated with the occurrence of renal disease." (PMID 36159576, 2022). "Aging is an important risk factor for renal diseases, and while Sirt6 is increasingly recognized as a key anti-aging enzyme, its role in the kidney remains completely unknown." (PMID 28351995, 2017). "These in vivo and in vitro findings demonstrate for the first time that Sirt6 has a crucial role in the maintenance of glomerular function, and consequently, may be an important, potentially new therapeutic target for renal diseases associated with aging." (PMID 28351995, 2017). "Podocyte-specific knockdown of Sirt6 exacerbates podocyte injury and proteinuria in adriamycin-induced nephropathy and DKD." (PMID 38347622, 2024). "Both SIRT-3 and SIRT-6 could serve as potential targets in managing kidney diseases, particularly in the rejection processes following kidney transplantation." (PMID 40142268, 2025). "If further studies are required to address the role of Sirt6 in kidney disease, we may use a kidney-specific inducible Cre mouse or CRISPR system." (PMID 35563783, 2022). "Our findings indicate that Sirt6 might be a potential therapeutic target in kidney diseases such as DN." (PMID 34122724, 2021).
heart disease (10 papers, 2017 to 2024). "As such, direct administration of these Sirt6-enriched exosomes can potentially serve as a noninvasive therapeutic option for patients suffering from heart disease." (PMID 38172884, 2024). "In this way, SIRT6 protects the heart, and a decreased SIRT6 expression is observed in failing hearts, indicating that disrupted histone deacetylase activity of SIRT6 can lead to cardiac disease." (PMID 33806509, 2021). "We evaluated the effects of Ang II and ACE2 deficiency on SIRT6 levels and regulatory roles of SIRT6 in AMPK/ACE2 signaling and Ang II-mediated heart disease by the use of ACE2-mutant and Ang II-infused hypertensive rats." (PMID 29069788, 2017). "Sirt6 activation is beneficial in alleviating various factors involved in heart disease." (PMID 33442387, 2020). "However, the exact role of SIRT6 in heart disease is poorly defined." (PMID 29069788, 2017). "SIRT6, an important NAD-dependent enzyme, is vital in the regulation of both aging and heart disease." (PMID 38259289, 2023). "Future studies are required to more precisely clarify roles of cross-talk between SIRT6 and ACE2 in cardiac injury and related heart diseases." (PMID 29069788, 2017). "However, the interaction between the SIRT6 and AMPK/ACE2 signaling in heart disease is poorly defined." (PMID 29069788, 2017). "Another discovery confirmed that Sirt6 has cardioprotective effect on cardiac fibrosis through upregulation of AMPK-ACE2 signaling pathway, implying that manipulating Sirt6 has promising therapeutic importance for cardiac fibrosis and cardiac diseases (Zhang ZZ." (PMID 37497437, 2023).
inflammation (9 papers, 2018 to 2024). Aberrant reaction of the microcirculation characterized by movement of fluid and leukocytes from the blood into extravascular tissues. "The same study also indicated that Sirt6-null mice develop chronic liver inflammation attributable to Sirt6 deficiency in immune cells and macrophages, and these cells express increased levels of MCP1, IL-6, and TNF108." (PMID 35296782, 2022). "In summary, the results reveal a critical effect of IL-1β signaling in vascular inflammation, senescence and TAA formation with Sirt6 deficiency." (PMID 37394473, 2023). "Mice with airway epithelial cell-specific deletion of Sirt6 are protected against allergen-induced airway inflammation and remodeling via inhibiting IL-17A-mediated inflammatory chemokines and mesenchymal reprogramming." (PMID 38135684, 2023).
kidney (4 papers, 2020 to 2022). "This study provides proof of concept that Sirt6 activators may be therapeutic agents for cholestatic liver injury and fibrosis." (PMID 32701506, 2020). "In summary, we have provided data demonstrating that Sirt6 suppression promotes mitochondrial fission by activating the ROCK1‐Drp1 signalling pathway, thus inducing kidney injury." (PMID 35842903, 2022).
blood cancer (2 papers, 2021 to 2022). "In addition to its role in solid tumors, SIRT6 regulates blood cancer in a similarly complex manner." (PMID 35463332, 2022).
gastrointestinal tumours (2 papers, 2020 to 2022). "However, Furthermore, decreased SIRT6 expression was found to be associated with a shorter overall survival (OS) in gastrointestinal tumours (GC and CRC) (HR = 1.83, 95% CI = 1.20–2.79, P = 0.939)." (PMID 35172823, 2022). "The results revealed that decreased SIRT6 was significantly associated with unfavorable OS (P < 0.05) and DFS (P < 0.05) in gastrointestinal tumors (P < 0.05), which validated the results of meta-analysis." (PMID 35172823, 2022).
neurological disease (2 papers, 2021 to 2022). "Since SIRT6 inhibitors may affect the development of neurological disorder, assessing SIRT6 activators in neurological disease models will be interesting, but so far there has been no report on this direction." (PMID 34650436, 2021).
bacterial infection (1 paper, 2024). "However, SIRT6 in ILC3s plays a detrimental role in gut inflammation and pathogenic bacterial infection." (PMID 39253083, 2024). "Our results suggest that SIRT6 may play a role in ILC3 function by regulating gut immune responses against bacterial infection and inflammation." (PMID 39253083, 2024).
hematological diseases (1 paper, 2022). "In an in silico approach, we conducted an analysis in the GEPIA database, and we validated the results of the present systematic review when we observed that the SIRT1, SIRT3, SIRT5 and SIRT6 genes are also up-regulated in onco-hematological diseases such as DBLC when compared with normal tissues." (PMID 36230534, 2022).
skeletal dysplasia (1 paper, 2016). Any Mendelian diseases that affects growth and development of the skeleton. "Overall, SIRT6 deficiency in mice resulted in skeletal dysplasia, BMD decrease, and bone resorption increase of whole body bone tissue." (PMID 27357320, 2016).
SIRT6 also shares sentences with these, for which no sentence is quoted: idiopathic pulmonary fibrosis (5 papers); fibrosis (4); Huntington disease (3); hypertrophy (3); serous ovarian cancer (3); ulcerative colitis (3); chronic heart failure (2); chronic lymphocyte leukemia (2); clear cell renal cell carcinoma (2); hypertrophic cardiomyopathy (2); lumbar spinal stenosis (2); periodontal disease (2); prediabetes (2); thyroid papillary carcinomas (2); abdominal aortic aneurysm (1); actinic keratosis (1); acute coronary syndrome (1); aging (1); alcohol (1); anemia (1); aortic aneurysm diseases (1); apical periodontitis (1); atrial fibrillation (1); bladder tumor (1); blepharoptosis (1); brain diseases (1); cardiac interstitial fibrosis (1); cataract (1); celiac disease (1); cognitive disorder (1).
A further 49 diseases each share a sentence with SIRT6 in 1 paper.